STAT5B (signal transducer and activator of transcription 5B)
Diseases named in the same sentence as STAT5B in open-access papers (continued):
Sharing a sentence is not in itself a finding about the gene and the disease.
cancer (82 papers, 2007 to 2025). A tumor composed of atypical neoplastic, often pleomorphic cells that invade other tissues. "Further examination of cancer-specific patterns revealed particularly strong associations between STAT5B expression and survival outcomes in certain malignancies." (PMID 41301421, 2025). "In human cancers, STAT5B has been implicated in both promoting and suppressing tumorigenesis, with its effects varying by cancer type and molecular context." (PMID 41301421, 2025). "Here, we conducted a systematic meta-analysis of STAT5B to evaluate its association with overall survival across cancers and to compare its prognostic role with that of STAT5A." (PMID 41301421, 2025). "Previous studies have shown an enrichment of IS in cancer-associated genes, such as STAT5B and BACH2, suggesting IS-driven expansion of infected cells." (PMID 34140517, 2021). "Contrastingly, multiple de novo somatic GOF mutations arise in STAT3 and STAT5B leading to cancer pathogenesis, and such mutations have been implicated in both solid and liquid tumors." (PMID 31717342, 2019). "Nevertheless, targeted disruption of STAT5A and STAT5B gives rise to distinct phenotypes in mice and only STAT5B has been reported to be a target of mutations in cancer." (PMID 30573779, 2019). "Mutations of upstream kinases, copy number gains, or activating mutations in STAT5A, or more frequently in STAT5B, cause altered hematopoiesis and cancer." (PMID 31690038, 2019). "Although STAT5b is involved in cancer proliferation, mutations of STAT5b to account for this increased biological activity have not been identified." (PMID 17997837, 2007). "Our finding that STAT5B’s strongest survival associations occur in cancers with frequent epigenetic dysregulation (e.g., DLBCL, LUAD) raises the hypothesis that uSTAT5B contributes to heterochromatin stability." (PMID 41301421, 2025). "STAT3, STAT5A and STAT5B have been implicated in several physiological and disease processes such as cell division, migration, survival, cellular responses to pathogens, breast development, inflammation and cancer." (PMID 31443474, 2019). "This substitution to the STAT3 cancer-associated genotype in STAT5B suggests that the protein may be more optimized for protein dimerization." (PMID 31717342, 2019). "Insights into mutation-specific changes in the transcriptome or methylome of STAT5B-GOF mutated cancer cells may open novel therapeutic avenues." (PMID 31690038, 2019). "Meta-regression further supported these findings, with cancer type emerging as a significant modifier of the STAT5B-survival relationship." (PMID 41301421, 2025). "To assess the prognostic relevance of STAT5B in cancer, we analyzed the relationship between STAT5B expression levels and survival using the Prognoscan database." (PMID 41301421, 2025). "Our analysis of STAT5B mRNA expression across 31 cancer types using the GEPIA2 database revealed significant downregulation in 13 cancer types (p < 0.01), representing 42% of the studied malignancies." (PMID 41301421, 2025). "To this end, we conducted a comprehensive meta-analysis of STAT5B expression and survival outcomes across a wide spectrum of cancers, employing the same rigorous bioinformatic pipeline previously applied to STAT5A." (PMID 41301421, 2025). "Evidence also suggests that STAT5B is involved in epithelial-mesenchymal transition (EMT) of cancer cells." (PMID 39763651, 2024). "STAT3 and STAT5A as well as STAT5B have pleiotropic roles in the body and can act as critical oncogenes that promote many processes involved in cancer development." (PMID 35229974, 2022). "The gene of STAT genes was altered in 1,003 (9%) samples; STAT1, STAT2, STAT3, STAT4, STAT5A, STAT5B, andSTAT6 were altered in 2.3%, 1.7%, 2.0%, 2.4%, 1.6%, 1.9%, and 1.9% of the demanded pan-cancer samples." (PMID 36176415, 2022).
cancer (continued). "The gain-of-function mutations in STAT3 and STAT5b genes up to now remain the most frequent abnormalities in LGLL, even if additional genetic lesions in STAT-related or cancer genes have been described." (PMID 32133291, 2020). "Similar to STAT3, STAT5B has been mostly reported to play a major role in the progression and pathogenesis of cancer, but expression and phosphorylation levels of STAT5B were not affected by TCN." (PMID 32422984, 2020). "Several of the key regulators of transcription involved in mesenchymal transformation (e.g., NF-κB, CEBP-β) upregulate under hypoxic conditions in cancer cells, and hypoxia activates the JAK2/STAT5b pathway in several types of cancer." (PMID 30621209, 2019). "It was found that preventing the expression of STAT3, STAT5A and STAT5B is related to the enhanced apoptosis in cancer cells." (PMID 31569687, 2019). "Their study found that HBx activated STAT5b, which further promoted cancer cell motility and invasiveness by inducing EMT." (PMID 29258558, 2017). "Recently, two somatic STAT5b mutations (N642H and Y665F) have been described in large granular lymphocytic (LGL) leukemia patients, emphasizing the role of STAT5 in cancer pathogenesis." (PMID 26717567, 2015). "Despite this gene has not been annotated to be related to oral cancer in GeneCards, both STAT5A and STAT5B belong to the STAT5 family the aberrant activity of which has been found to be related to various cancers." (PMID 26064958, 2015). "Our study also assessed the regulation of signaling molecules implicated in the growth, progression, differentiation, and migration of cancer cells, such as Jak2, STAT5b, insulin-like growth factor-1Rβ, and their phosphorylation status." (PMID 26084564, 2015). "The cancer-relevant transcription factors STAT5a and STAT5b are particularly challenging small-molecule targets because their SH2 domains are 93 % identical on the amino acid level." (PMID 25702814, 2015). "The elucidation of the roles of STAT5A and STAT5B furthers our understanding of potential mechanisms in cancer pathophysiology, neural disorders, and abnormal T cell immune function providing potential new targets to study in these diseases." (PMID 24497979, 2014). "Our result are in accordance with observations of other investigators who have also reported STAT5A and STAT5B overexpression on mRNA and/or protein level in cancer tissue – prostate, breast, colorectal, esophageal and lung – when compared to normal tissue." (PMID 25137041, 2014). "The new identification of these genes regulated by STAT5A and/or STAT5B has major implications for understanding the pathophysiology of cancer progression, neural disorders, and immune abnormalities." (PMID 24497979, 2014). "Differential expression or activity (or both) of STAT5a and STAT5b has been reported in other cancer model systems." (PMID 19630967, 2009). "Activation of STAT5a and STAT5b occurs in a variety of cancers including both hematopoietic cancers and solid tumors, such as those of the breast, prostate, lung, head and neck, and brain." (PMID 19630967, 2009). "Owing to their ability to regulate the expression of genes involved in cell-cycle regulation (cyclin D1, c-myc, and p21) and cellular survival (Bcl-XL), STAT5a and STAT5b have emerged as possible targets for cancer therapeutics." (PMID 17997837, 2007). "Although STAT5a and STAT5b play a fundamental role in normal growth and development of the mammary gland, both proteins are overexpressed or constitutively activated in cancers, including some breast cancer tumors." (PMID 17997837, 2007). "Although traditionally known for its role in growth hormone signaling and mammary gland development, STAT5b has emerged as a therapeutic target due to its pivotal role in cancer." (PMID 17997837, 2007).
cancer (continued). "By elucidating the shared and distinct functions of these two isoforms, we aim to provide a foundation for future mechanistic studies and to inform the development of stratified therapeutic approaches that account for STAT5B’s context-dependent roles in cancer." (PMID 41301421, 2025). "The variation in effect sizes across cancer types suggests that the prognostic value of STAT5B may depend on tissue-specific molecular contexts or differential roles in various oncogenic pathways." (PMID 41301421, 2025). "Therefore, targeting the yet unliganded N-terminal domain (NTD) represents an approach for the direct inhibition of STAT5B function that would open a possibility for pharmacological intervention to cancer progression." (PMID 39085342, 2024). "In addition, HLF and ARID5B were identified as TFs of Tregs in precancer stages (e.g., N_HPV, AAH, NEOLP, EOLP), while regulons such as FOXO1 and STAT5B were specifically detected in cancers (e.g., IDC, AIS, MIAC, IAC and PDAC)." (PMID 38645221, 2024). "Actually, STAT5B also suggested to be a prognostic biomarker in certain types of cancers." (PMID 36862902, 2023). "EGFR/JAK2/STAT5b is also included in PD-L1-dependent cancer cell proliferation, and targeting this signaling pathway in NSCLC could be interesting due to EGFR overexpression, which is highly associated with many NSCLC cells, including A549 and H460." (PMID 37998363, 2023). "In addition, the gene expression levels of STAT5A and STAT5B were found to be organ specific and were significantly higher in cancer cells derived from lymphoid and myeloid organs." (PMID 35186733, 2022). "Defective provirus integrations are enriched in proximity to some cancer-associated genes such as BACH2, MKL2, and STAT5B, but whether integration in the proximity of such genes favors clonal expansion remains to be determined." (PMID 34636876, 2021). "However, evidence suggests STAT5A and STAT5B play different functional roles in normal and cancer cell systems." (PMID 31684144, 2019). "Notably, both of these frequently cancer-associated mutation sites in STAT3 (Tyr640 and Asp661) are by default Phe and Ile respectively in STAT5B." (PMID 31717342, 2019). "Pyk2 could regulate AKT, STAT3, ERK, MEK1/2, Src, HER3, MAPK, EGFR, and STAT5b in EGFR signaling in different cancer types." (PMID 31368612, 2019). "Investigations to elucidate the mechanisms involved in STAT5B downregulation induced by these combination therapies might help to design new inhibitors that specifically target cancer cells addicted to oncogenic STAT5B signaling." (PMID 31861239, 2019). "Interestingly, it is known that STAT5A and STAT5B isoforms have distinct biological functions and the expression patterns of these proteins differ among many types of cancers cells." (PMID 25137041, 2014). "Interestingly, it seems that STAT5B particularly played a major role in cancer cell viability and growth." (PMID 23668334, 2013). "The levels of STAT5B positively associated with the infiltration of resting memory CD4+ T, resting mast, and naive B cells in most tumors; however, STAT5B negatively correlated with the infiltration of Tregs, gammadelta T cells, TFHs, activated NK cells, and memory B cells in different cancer types." (PMID 36176415, 2022). "Even though gain‐of‐function (GOF) mutations of STAT5B were reported in a minor fraction (3.6%) of CTCL patients, our WES data were negative for GOF JAK–STAT mutations, but we consistently found copy number gains of STAT3/5 representing a cancer genome hallmark for the majority of L‐CTCL patients." (PMID 36341492, 2022). "In the case of STAT5B, which is more frequently mutated in cancer, the influence of O-GlcNAc on phosphorylation could not be demonstrated, even in the presence of the strongly activating STAT5B N642H mutation." (PMID 30818760, 2019).
cancer (continued). "Since 2013, somatic STAT5B mutations were discovered in large granula lymphocytic leukemia (LGL), in T-promyelocytic leukemia (T-PLL), in acute T-cell leukemia (T-ALL) and hepatosplenic T-cell lymphoma (HSTL), where more mutations can be expected through progress in the cancer genome project." (PMID 25333255, 2014). "Then, to finalize the genes and protein products in question, we evaluated the crucial genes in the GEPIA database and finally confirmed MYLK, SOCS3, STAT5B, BIRC5, PLK1, and RAPGAP1 proteins significantly in this cancer database." (PMID 35928368, 2022). "TFs associated with PIK3CA mutations were involved in WNT signaling, epithelial–mesenchymal transition, and cancer stem cell transition, including ELF3, TFEC, STAT4, STAT5B, NFATC1, GLIS1, CDC5L and AR." (PMID 36243974, 2022). "For example, YTHDF1 expression had a strong association with STAT1 in Th1 cells, STAT6 in Th2 cells, STAT3 in Th17 cells, STAT5B in Treg cells, BCL6 in Tfh cells, and IRF5 in M1 macrophages in most cancer types." (PMID 34026603, 2021). "Conversely, 28 of cancer-related genes were downregulated by shNrf1, of which 6 genes (i.e., HIF1A, STAT5B, IGF1R, TGFBR1, ATRN, and FZD6) were upregulated by Nrf1α−/− to varying extents." (PMID 32273945, 2020). "Due to the increased activation of their stimulators, STATs are commonly constitutively active in disease and elevated activation of STAT3, STAT5A, STAT5B and in some cases STAT1, has been observed in most cancer types." (PMID 32915198, 2020). "In mechanistic cell studies, coffee polyphenols change the expression of STAT5B and ATF-2 modifying cyclin D1 levels in cancer cells." (PMID 27608040, 2016). "Genes labeled by IPA as being cancer related (COL18A1, STAT5B, CTDSPL) were also involved with infection as were genes involved in apoptosis and growth (CTDSPL, POLR2F, ZBTB16)." (PMID 18047719, 2007). "The consistency of results across different analytical approaches and the lack of detectable bias strengthen the case for STAT5B as a biologically and clinically relevant factor in cancer progression and patient outcomes." (PMID 41301421, 2025). "Across 31 cancer types, STAT5B was significantly downregulated in 13 and never upregulated, with higher expression consistently associated with improved survival." (PMID 41301421, 2025). "In addition, the distribution of STAT1, STAT2, STAT3, STAT4, STAT5A, STAT5B, and STAT6 expression in CD8+ T cells in pan-cancer were displayed, which presented that STAT1 and STAT2 had prominent up-regulation in CD8+ T cell with ISG IFIT1." (PMID 36968603, 2023). "The relationship between Tid1 and cancer progression has been extensively investigated in studies of HER2, c-Met receptor tyrosine kinase (MetR), signal transducer and activator of transcription 5 b (STAT5b), Akt, adenomatous polyposis coli, and galectin-7." (PMID 33233689, 2020). "We identify STAT5B, H3F3A, and PTK2B as candidate cancer genes in T-ALL." (PMID 24367274, 2013). "STAT5b and Twist have been reported to promote aggressiveness and EMT of cancer cells in HCC." (PMID 21533080, 2011). "Strikingly, no cancer type exhibited significant upregulation of STAT5B compared to normal tissue." (PMID 41301421, 2025). "Notably, no cancer type analyzed showed STAT5B overexpression, reinforcing its distinct biological and prognostic profile." (PMID 41301421, 2025). "Finally, we aimed to identify viable fragment starting points against signal transducer and activator of transcription 5B (STAT5B), an important transcription factor mediating or even driving cancer progression through hyperactivation or gain-of-function mutations." (PMID 39085342, 2024). "Additionally, the distribution of STAT1, STAT2, STAT3, STAT4, STAT5A, STAT5B, and STAT6 expression in CD4+ T cells in pan-cancer were also clearly illustrated, which showed that STAT1 and STAT2 expression were notably up-regulated in CD4+ Treg cell with marker OSA1 and CD4+ T cell with ISG IFIT1." (PMID 36968603, 2023).
cancer (continued). "Notably, no cancer type showed a significant increase in STAT5B expression." (PMID 41301421, 2025).
infection (16 papers, 2007 to 2025). The state of being infected such as from the introduction of a foreign agent such as serum, vaccine, antigenic substance or organism. "The expression of HIF-1α, Relish and Stat5b were significantly upregulated in the susceptible family at 0 and 6 h post-infection, demonstrating that these genes are potentially involved in defense and immune response of the susceptible family." (PMID 37143674, 2023). "The results of functional enrichment analysis, immune infection level analysis, correlation analysis and literature validation demonstrated STAT5B was closely associated with the evaluation of response to anti-PD-1 therapy." (PMID 32316408, 2020). "Moreover, Stat5b-deficient cell lines grew out with a delay of ~12 weeks post infection, whereas Stat5a-deficient cells required about 6 weeks to form a stable cell line similar to wt lines, which succeeded to 100% to grow into stable cell lines (12/12)." (PMID 30679796, 2019). "Our immunofluorescence analysis of the Stat5b gene, coincident with a substantial increase in spleen size and weight following LPS infection, suggests compensatory hyperplasia driven by the immune response." (PMID 38753026, 2024). "The upregulation of Stat genes following LPS infection, with particular emphasis on Stat5b, suggests their pivotal role in orchestrating the immune response in this species." (PMID 38753026, 2024). "STAT5b is the sole member of the STAT family that is phosphorylated in the cecum during the initial infection process (4-24 hours) by S. Enteritidis." (PMID 35846741, 2022). "In contrast, there was a significant reduction or failure in activation of type 2-related chemokines/cytokines (Cxcl12, Ccrl1, Il4, Il23a) and signature markers (Stat3, Stat5b, Stat6, Mrc1, Ahr) during infection." (PMID 34320039, 2021). "Interestingly, EBV upregulated STAT3 and STAT5A levels, in particular between days 4 and 21 post-infection, whereas STAT5B levels were relatively constant." (PMID 38683861, 2024). "Notably, Stat5b displayed significantly upregulated expression compared to the other genes after LPS infection, gradually increasing up to 12 h after infection and then decreasing at 16 h." (PMID 38753026, 2024). "However, the CD25-deficient and the STAT5b-deficient patients did not exhibit increased susceptibility of infection with mycobacteria." (PMID 29988287, 2018). "A recent study on host response to PEDV infection in IPEC-J2 revealed the high expression of the STAT family except STAT5B and STAT6 after infection." (PMID 36733428, 2022). "Several cytokine response elements including STAT5B, STAT6, and IL10RB contributed to enrichment of a number of pathways relating to response to infection." (PMID 34658838, 2021). "Furthermore, we detected integrations within or near STAT5B and FOXK2 genes during acute and/or chronic states, lending support to the notion that clonally expanded sites during ART treatment can be established early during infection." (PMID 32970634, 2020).